PCNA (proliferating cell nuclear antigen)
Diseases named in the same sentence as PCNA in open-access papers (continued):
Sharing a sentence is not in itself a finding about the gene and the disease.
tumor (continued). "This less aggressive phenotype is likely linked to reduced cell proliferation, assessed by a decreased staining of the proliferative marker PCNA in tumours, increased sensitivity to apoptosis, and strong inhibition in the EMT program observed in p140Cap expressing tumour cells." (PMID 28300085, 2017). "In the tumour cells, PTEN protein levels were comparable to those observed in adjacent normal tissue or WT adult brain, and PTEN is predominantly cytoplasmic instead of being nuclear (colocalized with PCNA as in normal tissue)." (PMID 28094268, 2017). "Finally, we found that overexpression of ANG2 resulted in changes in the expression of tumor formation-related proteins including vimentin, E-cadherin, Bim, PUMA, Bcl-2, Bax, Cyclin D1, PCNA and CD31." (PMID 27492854, 2016). "PCNA expression correlated with tumor weight in all groups, whereas TUNEL positivity was not different among groups." (PMID 26992208, 2016). "Erianin-treated tumor tissues showed significant increase of terminal dUTP nick end labeling (TUNEL)-positive cells and the level of cleaved caspase-3 and JNK phosphorylation, whereas the level of PCNA was decreased." (PMID 27253411, 2016). "Compared with controls, the sh-ZYG11A group showed less PCNA staining, suggesting that ZYG11A knockdown could inhibit tumor growth in vivo." (PMID 26771237, 2016). "The suppressive effect of TPS on tumor growth is also considered to be related to its inhibiting expression of vascular endothelial growth factor (VEGF) and proliferating cell nuclear antigen (PCNA) in H22 tumor tissue." (PMID 27809221, 2016). "Further, IHC analysis of excised tumor sections confirmed reduction in HSP70-2 and PCNA expression." (PMID 27658496, 2016). "PCNA and β-catenin positive nuclei were significantly higher in c-Cbl silenced xenografts indicating that reducing expression of c-Cbl in CRC tumor cells increases tumor cell proliferation." (PMID 27661103, 2016). "Interestingly, dual immunofluorescence for transgene-derived RANKL and PCNA expression reveals salivary gland tumor cells which are double positive for RANKL and PCNA expression along with tumor cells which are positive for either RANKL or PCNA expression." (PMID 26061636, 2015). "PCNA and Bcl-2 are downregulated in INMAP-overexpressing tumour tissues." (PMID 25635878, 2015). "For examples, HepPar-1 is helpful in determining whether the tumor cells are hepatocyte-derived; CD31 is an angiogenesis-related marker for identifying cancer tissue from normal tissue, and Ki67 (PCNA) is a marker indicating cell proliferation." (PMID 25889678, 2015). "Regardless of genotype, a correlation between tumor size and p-Akt and PCNA was observed, with larger tumors (>400 mm3) possessing higher relative levels of p-Akt and PCNA versus smaller tumors." (PMID 26345456, 2015). "Western blot analysis and subsequent measurements of band densities in different blots of tumor lysates indicate that treatment of mice with honokiol inhibited the levels of PCNA in tumors compared with the tumor samples from non-honokiol-treated control mice." (PMID 26020804, 2015). "Moreover, consumption of CAPE or CAPPE also suppressed the expression of malignant biomarker proteins, such as PCNA and FASN in tumor tissues." (PMID 24960186, 2014). "Furthermore, subcutaneous homografts models showed the increased tumor growth and tumor vascularization with the CCL18 stimulation, and the expression of Ki67, PCNA, and CD31 in CCL18 stimulation mice was also significantly increased." (PMID 25197632, 2014).
tumor (continued). "The recurrence/metastasis of HCC is closely related with clinical parameters such as the size of tumor, tumor capsule, tumor boundaries, portal vein tumor thrombosis (PVTT), intraoperative ascites, cirrhotic nodule, heteroploidy, PCNA (Proliferating Cell Nuclear Antigen) expression and others." (PMID 24839399, 2014). "PCNA and TUNEL were used to detect apoptosis of the tumor cells." (PMID 25033896, 2014). "However, despite the crucial character of the integrity of the DNMT1/PCNA/UHRF1 complex, the integrity of other DNMT1 including complexes plays a major role in the inheritance of DNA methylation and in tumor development and progression." (PMID 24637615, 2014). "Tumor tissues were then embedded in paraffin, stained with hematoxylin and eosin (H&E), and immunohistochemically stained with antibodies against FOXA1, AR, Notch1, Hes1, Ki67, or PCNA." (PMID 24512546, 2014). "PCNA and KIAA0101 were classical biomarkers in estimating malignant degree of tumor cells." (PMID 25333259, 2014). "Consistent with the relationship between elevated nestin expression and Ki-67 or PCNA expression in NSCLC tumor specimens, nestin knockdown in tumor cells resulted in a significant decrease in the number of Ki-67-positive cells compared to control tumor cells." (PMID 24498263, 2014). "Although proteins such as FANCD2, PCNA, notch receptor, and histones H2A and H2B were reported to be deubiquitinated by the WDR48·DUB complex, the cellular functions of WDR48 and its role in tumor suppression were not completely known." (PMID 24145035, 2013). "The anti-tumor effect of PXD101 may be through apoptosis and inhibition of proliferation since caspase-3 and PCNA were decreased." (PMID 24155971, 2013). "This may have been due to the decrease in the protein expression of MMP-9, PCNA and VEGF, and the increase in the TIMP-1 protein expression induced by SN50, in combination with the cytotoxicity of SN50 towards the tumor cells." (PMID 24137341, 2013). "Fra-1 and c-Fos over-expression is clearly observed in actively proliferating tumor samples (as evidenced by the high levels of PCNA immuno-reactivity) as compared to their non-pathological counterparts." (PMID 23301044, 2013). "This value was greater than the number of PCNA-positive cells observed in fresh tumor (48.8±13.5) but was not statistically significant." (PMID 24116092, 2013). "To investigate whether the proliferation of tumor cells was increased by CRS, we quantified the number of PCNA-positive cells." (PMID 23585898, 2013). "Interestingly, tumor cells in oral CIS lesions exclusively produce hBD-3, correlated with expression of proliferating cell nuclear antigen (PCNA) in these cells." (PMID 23060878, 2012). "PCNA and MCM7 were ectopically expressed in the lower epithelial suprabasal layers of CIN1, and their expression expanded upwards in CIN3, reaching almost all tumor cells in CC samples." (PMID 22911850, 2012). "Furthermore, the PCNA, PRKDC and RAD21 module is important to DNA repair as it also helps to suppress tumours." (PMID 23002138, 2012). "Tumour cells do not express cell proliferation markers such as Ki-67 and PCNA, indicating that the lesions are more likely hamartomas than neoplasms." (PMID 23259131, 2012). "Tumour sections from rats treated with LiCl or non-treated for control showed an relatively equal number of PCNA-positive cells." (PMID 21609428, 2011). "We observed a significant increase in TUNEL-positive apoptotic cells in tumours from rats that were treated with LiCl, while we did not see a decrease in the number of PCNA positive proliferating cells." (PMID 21609428, 2011).
tumor (continued). "Tumor-bearing mice with PTEN +/+ or PTEN −/− tumors were treated for 5 days (3−4 mice per group), and tumor tissue was analyzed by immunohistochemistry (IHC) for evidence of cell proliferation (anti-PCNA and anti-Ki67) and for cell death (TUNEL)." (PMID 21267448, 2011). "Since the mean PCNA positivity within primary tumors was 95% in the control group and 79% in the TGZ group, this indicates that a great majority of tumor cells in the control group were proliferating actively, whereas 21% of tumor cells in the TGZ group were arrested in the G1/G0-phase." (PMID 20170548, 2010). "Immunohistochemistry staining with PCNA and TUNEL assay of tumor tissue were performed." (PMID 20565783, 2010). "In HT-29 and THP-1 tumor cells an up to 15% reduction of mRNA expression for both genes (E2F-1 and PCNA) compared to control without treatment was detectable." (PMID 19551155, 2009). "Interestingly, a higher number of PCNA-positive compared to TUNEL-positive cells was observed in SBC-2-CXCR1 and SBC-2-CXCR2 tumours." (PMID 19401689, 2009). "In animal tumor models with high-expression levels of lymphatic vessel growth factor VEGF-C or VEGF-D, the endothelial cells along lymphatic vessels show proliferation and a positive stain for proliferating cell nuclear antigen (PCNA)." (PMID 19232130, 2009). "VEGF, NF-κB, PCNA, MMP-2 and MMP-9 expression in tumor tissue was also assessed." (PMID 18983651, 2008). "The cells showing ZsGreen fluorescence also showed decreased proliferation, as assessed by immunohistological detection of the proliferation marker PCNA, indicating that these cells represent the responding fraction of the tumour (data not shown)." (PMID 18000499, 2007). "The number of SN12C-VC or SN12C-VHL-KD tumor cells undergoing proliferation or apoptosis, as determined by PCNA and TUNEL staining, respectively, was not significantly different between the anti-CXCL12 and the control antibody treated mice." (PMID 17083723, 2006). "Op18 levels were negatively correlated with oestrogen receptor (OR) expression and positively correlated with a high fraction of aneuploid cells, proliferation measured by proliferating cell nuclear antigen (PCNA) expression, tumour size and histopathologic grade." (PMID 10917544, 2000). "The effects on tumours were examined by morphometry, in situ end labelling (ISEL) of apoptotic cells and immunohistochemically with monoclonal antibodies to proliferating cell nuclear antigen (PCNA) at different time points up to 168 h after castration." (PMID 7599043, 1995). "In tumor-bearing mice, PEG-HMS-DTX achieved superior tumor accumulation (peak at ∼12 h), pronounced tumor growth inhibition (>70%), minimal systemic toxicity, and elevated apoptosis characterized by increased cleaved caspase-3 and reduced PCNA/Bcl-2 expression." (PMID 41675220, 2026). "Moreover, IHC revealed that the ratio of Ki67-positive cells and PCNA-positive cells was higher in the XAB2 overexpression group, while the ratio was lower in the XAB2 knockdown group, supporting the role of XAB2 in promoting CRC tumor growth." (PMID 40069750, 2025). "In addition, tumor tissues were stained with H&E to observe tumor cell morphology, and immunohistochemistry (IHC) was performed to detect the expression level of p21, WWP2, CMTM6, the cell cycle promoter c-MYC, and the proliferation marker PCNA." (PMID 41387673, 2025). "Moreover, Ki67 and PCNA staining results indicated a significant reduction in the quantity of proliferation markers in the CJP–TiN+L group, indicating that this treatment approach effectively inhibited tumor cell proliferation." (PMID 40387011, 2025).
tumor (continued). "Additionally, analysis of BUB1 mRNA expression in the TCGA MPM dataset—as an indicator of tumor cell proliferation—revealed a strong positive correlation between BUB1 expression and well-established proliferation and cell cycle markers, Ki67, PCNA, CCNB1, and CDC20." (PMID 40180891, 2025). "To understand whether PGR levels might be regulating intratumoral cell proliferation via macropinocytosis, we measured the PCNA staining in PDAC tissue originating from non-peripheral or peripheral regions of xenograft tumor." (PMID 38424455, 2024). "Additionally, under low dietary methionine conditions, NR4A2 abrogation did not further impede ESCC tumor growth and decline intratumoral expression of PCNA and Cyclin B1." (PMID 38570607, 2024). "In addition, the TFAP2A level was positively related to important proliferative markers (Ki67, PCNA and HDNC1), which suggested that TFAP2A may promote the proliferation of tumours." (PMID 39695171, 2024). "Additionally, IHC staining demonstrated a decrease in the proliferative marker PCNA, while ER stress and apoptotic markers CHOP and Cyt C were elevated in tumor cells subjected to CSN5 inhibition, and 4-PBA involvement could reverse the trend." (PMID 38385070, 2024). "Unlike 5-FU, LMW-AP-FBG treatment did not reduce PCNA-positive cells in tumor tissues of CT-26 bearing mice, suggesting that LMW-AP-FBG treatment could not inhibit cell proliferation under an in vivo condition." (PMID 36831065, 2023). "Then we observed that the positive rates of Ki-67 and PCNA in RBE+M2 group were significantly higher than those in RBE group by immunohistochemical staining, which may be related to the role of M2 macrophages in promoting tumor cell proliferation." (PMID 37809069, 2023). "However, after RFA, rabbit VX2 liver tumor tissue showed complete necrosis, but the expression of PCNA and α-smooth muscle actin did not decrease compared to the tumor group." (PMID 36920938, 2023). "The immunohistochemical staining showed that compared with the AOM/DSS mice, the level of Ki67+, PCNA in AOM/DSS + SR‐B1−/+ mice was significantly reduced, while the level of CASP3 was significantly increased (p < 0.01), which indicated that SR‐B1 knockdown inhibits the growth of tumor cells." (PMID 37766594, 2023). "The immunohistochemical staining showed that compared with APCmin/+ mice, the level of Ki67+, PCNA in APCmin/++SR‐B1−/+ mice was significantly reduced, while the level of CASP3 was significantly increased (p < 0.01), which indicated that SR‐B1 knockdown inhibits the growth of tumor cells." (PMID 37766594, 2023). "As HOXD9 is an important transcription factor promoting tumor proliferation, we examined the correlation between HOXD9 mRNA levels and proliferation markers PCNA, Ki-67 as well as cell cycle related genes CCNA2 and CCNB1 to validate whether HOXD9 can facilitate ATC proliferation." (PMID 37974228, 2023). "Tumours growing in the brain of Glu-CB1R-KO mice exhibited a higher activation of NMDARs (as assessed by phosphorylation of the NMDAR2B subunit and the expression of the NMDAR-adaptor protein PSD-95) and an increased expression of the proliferation marker PCNA." (PMID 37173906, 2023). "Another molecule that promotes glycolysis is the proliferating cell nuclear antigen (PCNA), which is a nuclear protein synthesized in the early G1 phase and in the S phase of the cell cycle and is considered a marker of the proliferation index in some neoplasms." (PMID 37520325, 2023). "In the H226 xenograft, tumor growth was suppressed by DCA/Nic and partially mediated by apoptosis (downregulation of Bcl-2 and XIAP), anti-proliferation (decrease in expression of PCNA and Akt), G2/M arrest (CDK7 downregulation) and suppressed migration (decline in expression β-catenin)." (PMID 36304150, 2022).
tumor (continued). "In addition, the expression of PCNA and CDK2 was decreased by LncSIK1 in the tumour." (PMID 35092119, 2022). "Cancer cell proliferation may involve a non-oncogenic structural protein, such as PCNA, which acts as a “hub” for large cellular complexes that is essential for tumor growth and cancer cell survival." (PMID 35216113, 2022). "It is also notable that PCNA protein levels were relatively decreased in the siTEX11-treated tumors compared with siControl-treated tumors, suggesting that TEX11 silencing may repress the tumor proliferative activity." (PMID 36319719, 2022). "Since the proliferative and tumor stemness phenotypes were significantly affected by FAM64A inhibition, we next detected markers reflecting proliferation and cancer stemness, and found that the levels of PCNA, CD44, SOX2, and BMI-1 were all markedly decreased upon reduction of FAM64A." (PMID 35538067, 2022). "Ki-67, a proliferating cell nuclear antigen, is a measure of the fraction of cells entering the cell cycle and mitosis, often used to evaluate the proliferating fraction versus the non-proliferating fraction within a tumor." (PMID 35795681, 2022). "However, our data show that subcutaneous injection of MCF10A cells exposed to FolateRDI/Diuron3MAC/PFOA3MAC does not induce tumor formation as does the injection of MCF10A cells that have lost the integrity of the DNMT1/PCNA/UHRF1 complex." (PMID 36278678, 2022). "PCNA, VEGF, and other factors play important roles in promoting tumor proliferation and metastasis, PCNA is a cyclin, an accessory protein for cell DNA polymerase that exists in each developmental stage of tumor cells and the normal proliferation cycle of cells." (PMID 34257693, 2021). "Hence, a combination of inhibitors blocking both pathways could lead to a significant tumor growth reduction together with a decrease in proliferation indexes, including RB1 phosphorylation, E2F1, CCND1, and PCNA expression levels, in the NPC PDX model." (PMID 34204797, 2021). "Additionally, genes that are critical to cancer growth and metastasis, such as AURKB, PCNA, fascin, and FILIP1L, may also play a role in the cooperative anti-tumor activity of vitamin C and buparlisib." (PMID 33664847, 2021). "The proliferate rate of PCNA in CPDP NPs + LIFU group was only 20.50%, which was fourfold lower than control group, threefold lower than LIFU and CPDP NPs only group and twofold lower than PDP + LIFU group, respectively, demonstrating a significant anti-tumor proliferation rate." (PMID 33928450, 2021). "Fibrous tissue proliferation, inflammatory cell infiltration, tumor cell necrosis, and the expression of proliferating cell nuclear antigen (PCNA) and vascular endothelial growth factor (VEGF) were all lower than in the control group (VEGF P < 0.001 and PCNA P < 0.05)." (PMID 34257693, 2021). "This study then tested PCNA level in OS and found that inhibition of RDM1 suppressed PCNA expression compared with normal control group, indicating that knockdown of RDM1 inhibited tumour group, which is consistent with the results of tumour volume and tumour weight." (PMID 34264012, 2021). "Moreover, to further confirm the effect of DHX32/β-catenin pathway on HCC proliferation and EMT in vivo, we should also detect the expression of proliferation makers, such as PCNA, Cyclin D1, β-catenin expression, and EMT markers including E-cadherin and vimentin in the tumour tissues." (PMID 33729094, 2021). "Immunohistochemical staining with a PCNA antibody demonstrate that cell proliferation was drastically inhibited in the xenograft tumors treated with MBZ or cisplatin, while the combination of MBZ and cisplatin led to the greatest decrease in cell proliferation in the retrieved tumor masses." (PMID 34232919, 2021). "In addition, immunohistochemical (IHC) staining for proliferating cell nuclear antigen (PCNA) in subcutaneous tumour tissues indicated that upregulated BATF2 expression did not inhibit tumour cell proliferation." (PMID 33452462, 2021).